LINC00342 (long independently transcribed non-coding RNA 342)
Synonyms: formerly NCRNA00342
Gene: Long non-coding RNA gene on chromosome 2 (95,806,973 to 95,835,003, reverse strand). Ensembl gene ENSG00000232931.
Diseases named in the same sentence as LINC00342 in open-access papers:
LINC00342 is named in the same sentence as 14 diseases in open-access papers, as found by Europe PMC text mining. Sharing a sentence is not in itself a finding about the gene and the disease. The quoted sentences say what the papers report.
colon adenocarcinoma (2 papers, 2021 to 2024). "LINC00342 has been found to be upregulated in colon adenocarcinoma promoting cell proliferation and invasion, whereas LINC02691 and LINC00486 expression correlates with overall survival and prognosis in hepatocellular and gastric carcinoma, respectively." (PMID 39217365, 2024). "Another study found that high expression levels of LINC00342 was related the poor prognosis of colon adenocarcinoma patients and knockdown of LINC00342 suppressed the progression of colon adenocarcinoma." (PMID 34715819, 2021).
clear cell renal cell carcinoma (1 paper, 2025). "LINC00342 has shown a correlation between its overexpression and poor prognosis of patients with clear cell renal cell carcinoma, likely due to its role in the reprogramming of glucose metabolism and cancer metastasis." (PMID 41303378, 2025).
colorectal cancer (1 paper, 2021). A primary or metastatic malignant neoplasm that affects the colon or rectum. "However, the functional role of LINC00342 in colorectal cancer (CRC) remains unclear." (PMID 33588834, 2021).
lymph node metastasis (1 paper, 2022). "LINC00342 was determined as a poor prognostic biomarker of non-small cell lung cancer positively correlated with lymph node metastasis and TNM stages." (PMID 35661695, 2022).
renal carcinoma (1 paper, 2021). A carcinoma arising from the epithelium of the renal parenchyma or the renal pelvis. "LINC00342 was generally overexpressed in renal carcinoma cell lines as compared with HK-2 cells, and the overexpression was most obvious in 786-O cells." (PMID 35083240, 2021).
ZIKV infection (1 paper, 2017). "For example, LINC00963 and LINC00342, anti-apoptotic factors, are downregulated by ZIKV infection." (PMID 29116029, 2017).
tumor (4 papers, 2021 to 2024). "Expression of CCL28, APP, EHF and LINC00342, among others, is increased in LP cells relative to the basal tumor." (PMID 39478117, 2024). "In addition, IHC assay results showed that knockdown of LINC00342 obviously reduced the number of Ki-67 positive cells in tumor tissues compared with sh-NC (p < 0.01)." (PMID 34715819, 2021). "Moreover, knockdown of LINC00342 significantly reduced tumor volume (p < 0.05) and tumor weight (p < 0.01) compared with sh-NC." (PMID 34715819, 2021). "Hence, these findings indicated that knockdown of LINC00342 inhibited the tumor growth in vivo." (PMID 33588834, 2021). "Moreover, LINC00342 functioned as a tumor promoter by sponging miR-19a-3p and releasing NPEPL1." (PMID 33588834, 2021). "Among them, FAM30A, HCP5, LINC00963, TMEM147-AS1, and TTTY15 indicated a worse prognosis, but LINC00342, MEG3, HCG18, and N4BP2L2-IT2 demonstrated a better tumor prognosis." (PMID 35615374, 2022). "Our study further demonstrated that LINC00342 induced the proliferation and metastasis of CRC cells and tumor growth." (PMID 33588834, 2021). "Functional analyses revealed that the overexpression of LINC00342 partly overturned the tumor suppressive effects of NPEPL1 knockdown in CRC, indicating that LINC00342 accelerated CRC progression, at least in part, through regulating the expression of NPEPL1 by serving as a sponge of miR-19a-3p." (PMID 33588834, 2021).
cancer (3 papers, 2021 to 2025). A tumor composed of atypical neoplastic, often pleomorphic cells that invade other tissues. "LINC00342 has been demonstrated to affect the progression of several types of human cancer, but its function and underlying molecular mechanisms remains unclear." (PMID 34715819, 2021). "While AC156455.1 and LINC00342 demonstrated overexpression in cancer tissues, LINC00342 exhibited the most significant high expression." (PMID 35083240, 2021). "Despite of the oncogenic role of LINC00342 in other cancers, we confirmed its oncogenic role in GC, suggesting that LINC00342 might be a new target for drug development in GC treatment." (PMID 34715819, 2021). "LINC00342 was reported as an oncogene and correlated with cancer progression in various cancers." (PMID 35083240, 2021).
LINC00342 also shares sentences with these, for which no sentence is quoted: gastric cancer (2 papers); breast carcinoma (1); hemangioma (1); infantile hemangioma (1); non-small cell lung carcinoma (1); small cell lung carcinoma (1).